ST3GAL6-AS1 (ST3GAL6 antisense RNA 1)
Gene: Long non-coding RNA gene on chromosome 3 (98,706,236 to 98,733,597, reverse strand). Ensembl gene ENSG00000239445.
Diseases named in the same sentence as ST3GAL6-AS1 in open-access papers:
ST3GAL6-AS1 is named in the same sentence as 1 disease in open-access papers, as found by Europe PMC text mining. Sharing a sentence is not in itself a finding about the gene and the disease.
ST3GAL6-AS1 shares sentences with these, for which no sentence is quoted: myelomas (1 paper).